EZR (ezrin)
Diseases named in the same sentence as EZR in open-access papers (continued):
Sharing a sentence is not in itself a finding about the gene and the disease.
lung carcinoma (31 papers, 2010 to 2025). "Ezrin deficiency in highly metastatic human lung carcinoma 95D cells caused the reduction of the cell migration and invasion, and Src-FAK signaling is known to regulate the migration of cancer cells." (PMID 25866790, 2015). "A few studies to date have reported an association between ezrin/p-ezrin expression and clinicopathological parameters, as well as its prognostic role in lung cancer." (PMID 24629131, 2014). "Several previous studies have demonstrated that miR-183 regulates Ezrin expression in lung cancer cells and Ezrin expression has been associated with tumor invasion and metastasis." (PMID 22922800, 2012). "The underling molecular mechanism of Ezrin activation in lung cancer involves Ezrin modifications (such as phosphorylation and S-nitrosylation), epidermal growth factor receptor (EGFR), and EGFR-mediated signaling pathways in non-small cell lung cancer (NSCLC) cells." (PMID 33240887, 2020). "This interaction culminates in the establishment of a transcriptional complex that governs the expression of DSG3, subsequently influencing the invasive phenotype of lung cancer cells through the Ezrin pathway." (PMID 38900156, 2024). "(2015) suggested that ezrin exerted a vital role in the invasion of lung cancer within PDPN‐expressing CAF‐composed TME." (PMID 36156321, 2023). "Downregulation of Ezrin in lung cancer cells has resulted in actin cytoskeleton rearrangements, reduced EGFR activity and phosphorylation levels of downstream signaling pathways, as well as a substantial reduction in cell migration and invasion." (PMID 33240887, 2020). "It was also reported that piR-L-163 can interact with phosphorylated ezrin-radixin-moesin proteins, resulting in accelerated DNA synthesis and G2-M cell cycle accumulation in human lung cancer cell lines." (PMID 30636640, 2019). "In this regard, it is interesting to note that miR-96 also targets Foxf2 and Ezrin mRNAs, to block the invasion and metastasis of lung cancers and renal cancers." (PMID 30509302, 2018). "Elevated expression of ezrin has been reported in LTE, BE1, H446 and H460 lung cancer cell lines, and a substantial decrease in migration, proliferation and invasion was observed upon siRNA-mediated knockdown of ezrin." (PMID 26983550, 2016). "Ezrin expression correlates to an invasive phenotype in several carcinomas, including lung carcinoma, and in vitro, knockdown of Ezrin reduced the proliferation, migration, and invasion of cancer cells." (PMID 27344171, 2016). "The expression and clinical significance of ezrin in lung cancers have been related to phosphoezrin protein expression in tumor tissues found to be higher in precancerous tissues and in benign pneumonic tissues." (PMID 25866790, 2015). "The present study suggests that molecules involved in Src-to-ezrin signaling axis offer a new target for lung cancer therapy." (PMID 25866790, 2015). "Expression level of miR-183 was demonstrated to reversely correlate with the metastatic potential of lung cancer cells by targeting VIL2-coding protein ezrin and regulating the expression of other genes involved in migration and invasion." (PMID 22408395, 2012). "Ezrin upregulation was confirmed and considered an important regulator in lung cancer bone metastasis, which was induced by transforming growth factor β." (PMID 23209815, 2012). "MSN is a member of the ezrin–radixin–moesin family of proteins involved in various aspects of cell migration, adhesion, and invasion, and DPYSL3 and heat-shock chaperonin (HSP60) were linked to lung cancer metastasis." (PMID 35512017, 2022). "Additionally, in lung cancer cells, activated Ezrin facilitates mechanical transduction from the cytoskeleton to the membrane and regulates the malignant process in a tension-dependent manner." (PMID 33240887, 2020). "Highly expressed Ezrin has been detected in lung cancer cell lines and primary lung cancer tissues." (PMID 33240887, 2020).
lung carcinoma (continued). "Additionally, several direct targets of miR-183 have also been proposed, such as ezrin in lung cancer cells, together with Dkk-3 and SMAD4 in prostate cancer cells." (PMID 31210063, 2019). "In this context, it is worthwhile to mention that we have shown recently that cigarette smoke, a major cause not only for lung cancer but also for chronic obstructive pulmonary disease (COPD), provoked a decrease of AKAP12 and an increase of Ezrin expression in airway smooth muscle." (PMID 26202611, 2015). "Moreover, inhibition of Ezrin expression seem to reduce the chemotherapy resistance of human lung cancer cells, suggesting a potential AKAP-related strategy for this disease." (PMID 26202611, 2015). "Similarly, in human lung cancer cell line 95D, Ezrin short hairpin RNA arrested the cells in G0/G1 phases, which lead to the delay of cell cycle progression and inhibited cell proliferation." (PMID 26202611, 2015). "Overexpression of ezrin is associated with invasion and metastasis in head and neck squamous cell carcinoma (HNSCC), pancreatic carcinomas, ovarian cancer, breast cancer, ESCC, osteosarcoma and lung carcinoma." (PMID 23209815, 2012). "Importantly, ezrin has been reported to play an important role in the metastasis of lung cancers." (PMID 25866790, 2015). "In lung cancers, fusions with CD74 (83/216, 38.4%), EZR (28/216, 13.0%), SDC4 (26/216, 12.0%), and SLC34A2 (26/216, 12.0%) were highly frequent." (PMID 36369474, 2022). "Ezrin expression correlates to the degree of lymphatic metastasis, malignant phenotype, and advanced TNM staging of lung cancer patients significantly." (PMID 33240887, 2020). "In accordance, Ezrin knockdown by silencing RNA decreased cell proliferation and survival rate in tongue SCC cell line, human lung cancer cell lines, and colorectal cancer cell lines." (PMID 26202611, 2015). "Our ongoing studies include the investigation on the ouabain-induced signaling such as Src, ezrin, FAK, and p130CAS in other lung carcinoma cells including H460 cells." (PMID 25866790, 2015). "A recent study found that expression levels of profilin, fascin, and ezrin mRNA in patients with NSCLC lymphocyte metastasis are significantly increased, indicating that increased levels of these ABPs connected with metastasis or invasion of lung cancer cells are used as predictors of lung cancer." (PMID 34194957, 2021).
ovarian carcinoma (26 papers, 2011 to 2025). A malignant neoplasm originating from the surface ovarian epithelium. "The overexpression of ezrin has been linked to higher metastatic potential and poor clinical outcomes in patients with ovarian cancer." (PMID 40723199, 2025). "As a result, the miR-138/ezrin regulation axis is an important route via which miRNAs can influence the invasive aggressiveness of ovarian cancer cells." (PMID 40723199, 2025). "Like ezrin, cofilin is overexpressed in numerous malignancies, including breast and ovarian cancers." (PMID 38673965, 2024). "A previous study indicated that high mRNA and protein levels of ezrin in clinical ovarian carcinoma (OC) specimens of malignant effusions were observed when compared to solid tumors, including primary tumors and solid metastases." (PMID 35625426, 2022). "Since both breast and ovarian carcinomas exhibit a similar ability to disseminate due to malignant effusion formation, the significant increase of Ezrin serves as a future therapeutic intervention target." (PMID 33240887, 2020). "Increasing the expression of these miRNAs in ovarian cancer cells decreased the expression level of the EZRIN protein, suggesting that the inhibition of EZRIN through miR-183 and miR-22 as tumor suppressors plays a role in inhibiting ovarian cancer metastasis." (PMID 31035447, 2019). "The significantly elevated ezrin expression in effusions of both breast and ovarian carcinomas points out towards ezrin as a possible target for therapeutic intervention against malignant effusions." (PMID 27622508, 2016). "Ezrin, has been investigated in a large study of ovarian cancerwhere its expression was reduced in 440 ovarian cancer samples compared to normaland lower expression was associated with higher grade and shorter survival althoughnot in a multivariate analysis." (PMID 21423607, 2011). "Corroborating these results, a better outcome was also observed for patients with ovarian cancer and positive for ezrin." (PMID 21785570, 2011). "Literature review found Cofilin 1 (CFL1), Ezrin (EZR), Cyclophilin-A (CYPA), Profilin 1 (PFN1), Napsin A (NAPSA) have been found to be associated with the development and progression of OC15–19, and are potential TAAs for ovarian cancer." (PMID 38684875, 2024). "The treatment of ovarian cancer cells with LPA also promotes O-GlcNAcylation of ezrin–radixin–moesin (ERM) cytoskeletal proteins, and although the exact mechanism is not entirely understood, LPA-induced activation of ERM suggests the role of LPA in the adhesion and migration of ovarian cancer cells." (PMID 38607068, 2024). "Ezrin is a potential therapeutic target for improving the efficacy of ICIs against ovarian cancers." (PMID 35566582, 2022). "Moreover, VEGF also increases the expression of miR-205 in ovarian cancer cells, reduces ezrin and lamin A/C, and promotes the proliferation and metastasis of ovarian cancer cells." (PMID 31035447, 2019). "Previous reports have linked overexpression of ezrin and prognosis in various cancers, including ovarian carcinoma, hepatitis B-related hepatocellular carcinoma, non-small-cell lung cancer, and CRC." (PMID 29291001, 2017). "In ovarian carcinoma, weak or absent ezrin expression in serous ovarian carcinoma has been associated with an unfavorable prognosis in patients." (PMID 24959233, 2014). "The study showed that Ezrin protein was overexpressed in OC tissues and cells compared with normal controls, with the highest expression in metastatic tissues and cells, and positively regulates the proliferation, invasiveness and epithelial mesenchymal transformation of ovarian cancer cells." (PMID 38684875, 2024). "Although each alteration is infrequent, ROS1 fusions with many kinds of 5′ partner genes (CCDC6, CD74, EZR, KDELR2, LRIG3, SDC4, SLC34A2 and TPM3) have been reported in lung, brain, biliary tract, and ovarian cancers." (PMID 23418494, 2013).
ovarian carcinoma (continued). "Actually, previous reports have shown that Ezrin and its binding protein NHERF1 were upregulated in response to estrogen in breast and ovarian cancers, implying that there might be a potential link between Ezrin and estrogen or ER." (PMID 36386154, 2022). "Here, we reveal the involvement of the ezrin/radixin/moesin (ERM) family, which crosslinks transmembrane proteins with the actin cytoskeleton by serving as a scaffold protein, in the plasma membrane expression of PD–L1 in the human epithelial ovarian cancer cell line A2780." (PMID 35566582, 2022).
colorectal cancer (25 papers, 2012 to 2026). A primary or metastatic malignant neoplasm that affects the colon or rectum. "Meta-analysis of 7 studies on colorectal cancer showed significant association between high Ezrin expression and tumor grade, TNM stage, lymph node involvement and distant metastasis." (PMID 29190988, 2017). "Previous studies have reported that Ezrin overexpression was associated with poor prognosis in many malignancies such as ovary cancer, salivary gland cancer, breast cancer, colorectal cancer, hepatocellular cancer and lung cancer." (PMID 29190988, 2017). "Moreover, SIX1 and ezrin are significant independent prognostic factors in colorectal cancer, and ezrin expression is associated with colorectal cancer metastasis." (PMID 34771571, 2021). "In colorectal cancer, Ezrin expression was associated with tumor grade (OR 3.94, 95% CI 2.10–3.78), TNM stage (OR 5.66, 95% CI 1.41–22.67), lymph node metastasis (OR 9.52, 95% CI 3.93–23.02), distant metastasis (OR 3.06, 95% CI 1.77–5.31), disease free survival (HR 2.48, 95% CI 1.44–4.28)." (PMID 29190988, 2017). "In addition, Ezrin expression was found to be significantly associated with DFS in colorectal cancer." (PMID 29190988, 2017). "Interestingly, high ezrin expression was previously correlated with BRAFV600E mutation status in colorectal cancer since high ezrin immunohistochemical staining was found predominantly in BRAFV600E-mutated tumours (52%) in comparison with BRAF wild-type tumours (17%)." (PMID 37629086, 2023). "Moreover, high ezrin expression has been associated with BRAF mutation in colorectal cancer." (PMID 34198671, 2021). "Previous research has confirmed that circCDYL2 promotes migration in colorectal cancer by binding to Ezrin and activating the AKT pathway." (PMID 38654320, 2024). "The ezrin corner score (ECS) which represents the expression of ezrin in poorly differentiated clusters seems to be of potential value for the prognosis of colorectal cancers." (PMID 35328667, 2022). "Our study differs from other studies that was done for evaluating ezrin immunohistochemical stain in colorectal cancer in that we did complete digitalization of the immunostained slides and analyzed ezrin expression by quantitative method." (PMID 32334457, 2020). "Ezrin expression is higher in colorectal cancer tissues than in adjacent normal mucosa and the high level of ezrin expression is closely related to the colorectal cancer invasion and metastatic process." (PMID 32334457, 2020). "Ezrin IHC expression was focally positive in the adjacent normal mucosa, but its expression was significantly higher in colorectal carcinoma tissue." (PMID 32334457, 2020). "It will be necessary to carry out similar studies on a larger sample size in order to elucidate the possible prognostic significance of ezrin in colorectal carcinoma and ensure the ability of digital pathology to transform the practice of diagnostic pathology." (PMID 32334457, 2020). "The ezrin protein correlates with tumor invasiveness, metastasis and clinical prognosis in numerous types of human cancer including colorectal carcinoma." (PMID 32334457, 2020). "Ezrin expression is significantly associated with tumor grade, TNM stage, and lymph node metastasis in gastric and colorectal cancers." (PMID 29190988, 2017). "In total, 7 studies each yielded data on Ezrin expression in gastric and colorectal cancers, while 5 studies provided information on Ezrin expression and esophageal cancer." (PMID 29190988, 2017). "Ezrin protein expression is a promising biomarker in estimating the outcome of stage II colorectal cancer patients." (PMID 28953975, 2017). "In this study the applicability of ezrin protein expression together with MSI status and BRAF mutation status were tested in predicting disease outcome in stage II colorectal cancer." (PMID 28953975, 2017).
colorectal cancer (continued). "First, this study indicates that high Ezrin expression is related to tumor grade/TNM stage/lymph node metastasis in patients with gastric/colorectal cancer." (PMID 29190988, 2017). "Second, the pooled data of 4 studies showed significant association between high Ezrin expression and the TNM stage of colorectal cancer (OR = 5.66, 95% CI = 1.41–22.67, P = 0.014)." (PMID 29190988, 2017). "Ezrin binds cell-neural adhesion molecule (L1-CAM) to promote progression of colorectal cancer in that RNA interference of ezrin activity inhibited tumour metastasis mediated by L1-CAM." (PMID 26983550, 2016). "Ezrin has a role in colorectal cancer progression and it might provide clinically valuable information in predicting the behavior of colorectal cancer." (PMID 32334457, 2020). "This points to the role of ezrin in colorectal cancer progression and that ezrin might provide clinically valuable information in predicting the behavior of colorectal cancer." (PMID 32334457, 2020). "In our study, ezrin was expressed in 92.2% of the studied cases of colorectal carcinoma." (PMID 32334457, 2020). "The interaction of L1CAM with ezrin, and downstream activation of NF-κB is elevated in invasive colorectal tumor fronts and is necessary for proliferation, invasion and metastasis of colorectal cancer cells." (PMID 31455004, 2019). "There were 7 studies concerning Ezrin expression and colorectal cancer." (PMID 29190988, 2017). "Second, Ezrin is capable of predicting distant metastasis in colorectal cancer." (PMID 29190988, 2017). "Inhibition of EZR expression reduced adhesiveness in colorectal cancer cells." (PMID 27846905, 2016). "Additionally, the proproliferative effects seen after L1CAM overexpression in our study could possibly be induced through the upregulation of ezrin, as in colorectal cancer, ezrin also mediates proliferation, motility, and metastatic capacity via L1CAM." (PMID 34228897, 2022). "In this work, we studied ezrin expression by immunohistochemical staining of 51 cases of colorectal carcinoma and we found that it was higher in CRC tissues than that in the adjacent normal colorectal mucosa." (PMID 32334457, 2020). "First, the pooled data of 5 studies showed that high Ezrin expression was significantly associated with tumor grade in colorectal cancer (OR = 3.94, 95% CI = 2.10–7.38, P = 0.000), where no significant heterogeneity among studies was observed (I2 = 0.0%, P = 0.446)." (PMID 29190988, 2017). "Third, the combined data of 3 studies showed that high Ezrin expression was significantly associated with lymph node metastasis in colorectal cancer (OR = 9.52, 95% CI = 3.93–23.02, P = 0.000), with no significant heterogeneity among studies observed (I2 = 0.0%, P = 0.902)." (PMID 29190988, 2017). "ERM proteins (including ezrin) function as an AKAP to mediate axon guidance in neuroblastomas in the netrin and its receptors, which are deleted in colorectal cancer (DCC) signaling." (PMID 35328667, 2022). "The hsa_circ_0004087 has been proved to have the potential of binding Ezrin and activating the AKT pathway and promote colorectal cancer migration." (PMID 35295950, 2022). "The activation of NF-κB by L1CAM-FL through ezrin can activate the metalloendopeptidase CD10/neprilysin which subsequently confers proliferation, motility and metastatic capacity in colorectal cancer." (PMID 31455004, 2019). "Respectively, 5/4/3/3 studies provided data on Ezrin expression and tumor grade/TNM stage/lymph node involvement/distant metastasis in colorectal cancer." (PMID 29190988, 2017). "Also, the pooled data of 3 studies showed that high Ezrin expression was significantly associated with distant metastasis in colorectal cancer (OR = 3.06, 95% CI = 1.77–5.31, P = 0.000), where no significant heterogeneity among studies was noted (I2 = 0.0%, P = 0.530)." (PMID 29190988, 2017). "Two studies examined Ezrin expression and disease-free survival (DFS) in colorectal cancer." (PMID 29190988, 2017).